IL5 (interleukin 5)
Diseases named in the same sentence as IL5 in open-access papers (continued):
Sharing a sentence is not in itself a finding about the gene and the disease.
infection (continued). "There are no statistical differences in nearly all inflammatory markers when compared to their infection-naïve CF counterparts, except in the Th2-derived IL-4 and IL-5 which demonstrate significant decreases following exposure (p = 0.046, p = 0.045)." (PMID 34475490, 2021). "Decreased IFN-γ (Th1 cytokines) and increased IL-4, IL-5, and IL-10 (Th2 cytokines) during infection with S. mansoni suggested an imbalance in lymphocyte function." (PMID 34161342, 2021). "Although T helper cells play a central role in the induction of a protective immune response against infections from viral pathogens, Th2 cells producing interleukin (IL)-4, IL-13 and IL-5 can be detrimental in an infection." (PMID 33924141, 2021). "In our study, ST2-/- mice decreased the concentration of IL-5 and increased IL-33, IL-13 and IL-17 in the initial stage of infection, and with 63dpi in addition to IL-33 and IL-17, also increased IL-1β concentration." (PMID 34324507, 2021). "Both ILC2 numbers and their ability to produce IL-5 peak following virus clearance and during the 8 to 10 days post-infection recovery phase." (PMID 34960631, 2021). "Analysis of the bronchoalveolar lavage fluid (BALF) revealed elevated levels of IL-4 on days 0, 1, 2, and 5, and IL-5 on days 0 and 5 post-infection." (PMID 33653328, 2021). "First, an obvious increase in the levels of IFN-γ, IL-6, IL-1β, IL-1Ra, IL-18, IL-5, IL-8 was detected in the early (3 dpi) stage of infection, indicating the activation of innate immune responses, such as monocytes and NK cells." (PMID 33180882, 2020). "As a cytokine to mediate B cell differentiation, IL-5 level in the spleen was sharply reduced at the later stage of EBIV-infection, even undetectable on 5 d.p.i, indicating the damage of B cell function caused by EBIV." (PMID 33597934, 2020). "We and others have shown that Brugia experimental infections stimulate high levels of IL-5 systemic responses." (PMID 32571840, 2020). "In the rat model of schistosomiasis, primary infection and secondary infection induce a Th2 cytokine response characterized by increased expression of IL-4, IL-5, and IL-13, which is driven by egg production in mice." (PMID 33013763, 2020). "On day 5 post infection the Th2 cytokine IL-5 and the pro-inflammatory cytokine IL-6 were massively upregulated in IFN-γOFF mice as well as G-CSF and CCL-5 when compared with infected WT controls." (PMID 32023327, 2020). "At 5 days after infection, IL-6 and G-CSF were increased in males, whereas IL-5 and G-CSF were reduced in S. epidermidis infected females compared to control animals." (PMID 32373108, 2020). "IFN‐γ and IL‐5 synergize to enhance worm killing in late‐stage infection of BALB/c mice, indicating a cooperation of Th1 and Th2 cells leading to worm killing." (PMID 32145033, 2020). "Subsequently, neutralization of IL-25 during the course of infection or use of IL-17RB deficient mice reduced airway mucus measured by PAS staining, and accumulation of IL-5 and IL-13 measured in re-stimulated draining lymph node cell supernatants." (PMID 32397226, 2020). "Further evidence comes from primary infection of IL‐5–deficent BALB/c mice, which have much greater late‐stage worm numbers and higher blood mF." (PMID 32145033, 2020). "While this work does not definitively show a necessary role for ILC2s in clearance, it suggests that these cells are important for IL-5, IL-13, and amphiregulin production and coordination of eosinophilia in the lung during infection." (PMID 31072011, 2019). "Specifically, IL-5 and IL-13, which have been shown to activate the defense response to C. neoformans infection, were significantly induced in the mouse infection assay." (PMID 31329596, 2019). "The lack of protection in the Ph. sergenti SGH-immunized mice against infection correlates with a low ratio of IFN-γ to IL-5 production in the dLN during infection." (PMID 30633742, 2019).
infection (continued). "This raises the possibility of capture (and consumption) of IL-5 by IL-5R expressing cells that infiltrate the lungs during the recovery phase of infection starting at 8 d.p.i." (PMID 31415658, 2019). "The role of intestinal ILC2 during pathogen infection is to promote intestinal epithelium integrity via IL-5, IL-13, and amphiregulin, which leads goblet hyperplasia and mucus production." (PMID 30770814, 2019). "The proinflammatory cytokines TNF-α, IFN-γ, IL-1β, IL-2, IL-5, and IL-6 also showed high levels of expression during the infection period, suggesting that the balance between cytokines determines the course of infection." (PMID 31636507, 2019). "Analysis of anti-inflammatory cytokines revealed a peak of IL-4 and IL-5 in cerebra of T. canis-infected mice in the subacute phase of infection, decreasing to homeostatic conditions as of day 42 pi." (PMID 31315623, 2019). "Two months post infection, protection was associated with a significant increase in the ratio of IFN-γ to IL-5 expression in the dLN compared to controls." (PMID 30633742, 2019). "We have previously shown that ILC2 cells are recruited to the respiratory tract of mice following influenza A virus (IAV) infection and produce large quantities of IL-5 beginning 4-days post infection (d.p.i)." (PMID 31415658, 2019). "In the present study we directly compared the impact of IL-4R, IL-5, eosinophils (dblGATA) and both IL-4R + IL-5 on the infection with the filarial nematode L. sigmodontis." (PMID 31109364, 2019). "In immunized mice, increase in immune cytokines (IL-12p70, IL-4, IL-5, and IL-17A) induced by SPY1 were further upregulated by P17 treatment, whereas the decrease in the infection-associated inflammatory cytokine TNF-α by SPY1 was reversed." (PMID 30116243, 2018). "Murine infection with the lung migrating nematode, Nippostrongylus brasiliensis, elicits a strongly polarised type 2 response, characterised by IL-4, IL-13, IL-5 and IL-9 cytokines." (PMID 30500858, 2018). "The blockade of IL-5 completely abolished the protective effect of S. venezuelensis pre-infection on N. brasiliensis infection." (PMID 30283458, 2018). "At day 6 post-infection the increase in Il5 and Il13 mRNA expression in total lung was significantly reduced following anti-Ym1 treatment whilst Il4 was not significantly altered." (PMID 30500858, 2018). "The increase in immune cytokines (IL-12p70, IL-4, IL-5, and IL-17A) induced by SPY1 were further upregulated by P17 treatment, whereas the decrease in the infection-associated inflammatory cytokine TNF-α by SPY1 was reversed." (PMID 30116243, 2018). "After infection we found reduced IL-5 (p < 0.001) levels in the immunized groups with the extracts compared to mice in the control group, which had been immunized with PBS and subsequently infected with Ascaris (PBS-ASC)." (PMID 30473693, 2018). "Further, serum levels of interleukin (IL)-2, interferon γ, tumor necrosis factor (TNF)-α, IL-12p70, IL-22, IL-17A, and IL-5 increased significantly after infection." (PMID 30564216, 2018). "Increased differentiation of Th1 and Th17 cells after fbp1Δ mutant yeast infection was accompanied by decreased differentiation of IL-4 -, IL-5 -, and IL-13 -producing Th2 cells compared to H99 infection." (PMID 29317510, 2018). "To investigate lymphocyte activity after infection, we quantitatively determined the presence of IL-2, IFN-γ, TNF-α, IL-4, IL-5, IL-17A, IL-12p70, and IL-22 in mouse sera at day 3, 5, 7, and 9 post-infection; the sera of healthy mice were used as controls." (PMID 30564216, 2018). "There were no significant changes in the secretion of the type II cytokine IL-4, but type II cytokine IL-5 was increased post-infection; the RH group had lower IL-5 levels than the ME49 group at day 5 and 9 post-infection." (PMID 30564216, 2018). "Accordingly, pre-infection with S. venezuelensis also enhanced the expression of mRNA for IL-5 and IL-13 in the lungs." (PMID 30283458, 2018).
infection (continued). "This type of infection elicits a Th2 immune response which results in IL-5 production, an essential cytokine for eosinophil differentiation." (PMID 28095898, 2017). "The magnitude of the IFN-γ response to infection is relatively large compared to type 2 cytokine induction, but induction of IL-5 and IL-13 is more selective for allergic asthmatics compared to controls." (PMID 28373098, 2017). "The induction of a prevalent Th2-type response, with the production of IL-4, IL-5, and IL-13, results in a less robust and less efficient reaction to the infection, clinically presenting as increased disease severity and risk for future recurrent wheezing." (PMID 29206851, 2017). "Levels of IL-5 and IL-13 in nasal lining fluid tend to be high before infection (day 0) in those individuals that developed the highest levels after rhinovirus infection." (PMID 28373098, 2017). "A lower Th1/Th2 ratio and higher cytokine response ratios for IL5 and IL13 during maintenance therapy were also significantly associated with increased risk for infection." (PMID 29051761, 2017). "Anti‐inflammatory cytokine IL‐5 decreased in the CMV lytic infection group (35.6 ± 4.6 vs control 48.7 ± 3.2, P = 0.032)." (PMID 29226079, 2017). "The identification of IL-5 as a key molecule in reducing immunity to autoantigens, some infections, vaccines, and exacerbating responses to allergens, makes IL-5 a target to block and restore protective or less destructive immunity." (PMID 29163523, 2017). "Nasal IL-5 and IL-13 levels were generally < 1 pg/ml in healthy controls, but higher at > 1 pg/ml in most stable allergic asthmatics prior to infection." (PMID 28373098, 2017). "We have previously reported that bronchial levels of IL-5 and IL-13 were greater during infection in asthmatic compared with healthy subjects." (PMID 28373098, 2017). "Cytokine response ratios were evaluated for patients with and without subsequent infection and only cytokine response ratios for IL5 and IL13 were significantly associated with increased risk for infection (p = 0.01 for both)." (PMID 29051761, 2017). "infection induced Th2-biased immune responses with elevated synthesis of IgE and IgG1 and an increased splenocyte production of IL-5, IL-10 and IL-13." (PMID 28606183, 2017). "This revealed 13 mediators of inflammation that correlated with infection status, which were, in order of strength of significance, IL-4, IL-5, IL-7, IL-15, IFN-α, IL-12, IFN-γ, IL-17, IL-1Ra, TNF-α, IL-1β, IL-10, and IL-2." (PMID 27418744, 2016). "Restricting Il4 deficiency to ILC2s in vivo revealed an important role of ILC2s for the differentiation of IL-13+ and IL-5+ TH2 cells following infection with H. polygyrus." (PMID 26883724, 2016). "In the livers of animals infected with HA-MARV, the pro-inflammatory cytokines TNF-α and IL-6, as well as the Th2 cytokines IL-4 and IL-5 and the Th1 cytokine IL-12, were all elevated early before decreasing over the course of infection." (PMID 27976688, 2016). "After an initial schistosome-induced production of the Th1 cytokine (IFN-γ), Th2 cytokines such as IL-4, IL-5 and IL-13 are generated in response to established infections." (PMID 27152725, 2016). "On the other hand, the IL5 mRNA was upregulated by infection in CS but barely detectable in CHB at the sequencing depth in this study." (PMID 27197554, 2016). "The generation of antigen-specific Th1 responses before infection was verified by measuring IFNγ and IL-5 after incubation of spleen cells from cohorts of immunized mice with their relevant immunizing antigen (data not shown)." (PMID 27142329, 2016). "On the other hand, Th2-like cytokines such as IL-4, IL-5 and IL-13 are predominant in immune responses to the chronic phase of infection which induce alternative activation of MΦs and upregulate the ADCC response." (PMID 26578348, 2015).
infection (continued). "AVP vaccination was found to result in a polarized IFNγ CD4+ T cell response, while the individuals exposed to B. anthracis by natural infection mounted a broader cytokine response encompassing IFNγ, IL-5, −9, −10, −13, −17, and −22." (PMID 26075052, 2015). "The cytokines IL-4, IL-5 and IL-10 are thought to balance the pro-inflammatory milieu generated in an infection to keep the host tissue safe from its own inflammatory immune responses." (PMID 26566996, 2015). "The results related to IL-5 revealed an early, significant and progressive increase in this cytokine from the 3rd day of infection until the 7th day p.i., which then decreased to baseline values." (PMID 26135397, 2015). "Th2 cytokines such as IL-5 and IL-10 were found to be increased during the early stages of infection (days 3–4 pi), while Th1 cytokines such as IL-6, IFNγ, and IL-18 did not increase until later in disease (days 6–9 pi)." (PMID 26512687, 2015). "The up-regulated expression of IL-4, IL-5, IL-10, and IL-13 showed Th2 cell predominance in immunopathological reactions at late infection phase in response to infection by A. cantonensis." (PMID 26070790, 2015). "We note that IL-12 and IFNγ (a Th1 cytokine response), and IL-10, IL-4, IL-13 or IL-5 (Th2 cytokine response) were either down-regulated during the latter phase of infection or remained unchanged." (PMID 25719526, 2015). "Historically, low levels of T cell cytokines (IL-2, IL-3, IL-4, IL-5, IL-9, IL-13) have been observed in fatal human cases of infection with EBOV and in infection of NHPs with MARV." (PMID 26512687, 2015). "Macrophages, eosinophils and lymphocytes gathered at the site of inflammation and Th2-type cytokine secretion such as IL-4, IL-5, IL-10, and IL-13 were increased under the stimulation of worm antigen in the late infection phase." (PMID 26070790, 2015). "IL-4 cytokine levels peaked with the onset of microfilaremia at 60 dpi, whereas IL-5, IL-13 and IL-25 levels increased with the duration of infection." (PMID 24663956, 2014). "In our study, after infection with S. japonicum for three weeks, cytokines (such as IL-4, IL-5, IL-6, IL-13, TNF-α and GM-CSF) in the sera of M. fortis were significantly increased, whereas cytokine levels of the BALB/c mice were much lower (data not shown)." (PMID 24886088, 2014). "The observed difference in levels of transcripts for IL-4 and IL-5 in the abomasal mucosa following infection of yearlings with T. circumcincta is consistent with studies of H. contortus infection of sheep and O. ostertagi infection of cattle." (PMID 24712712, 2014). "Significant Th2-type responsiveness was seen from week 7 of infection onwards, after the onset of oviposition, with IL-4 and IL-5 rising ahead of IL-13." (PMID 25398130, 2014). "The Th2 cytokines IL-5 and IL-13 increased steadily from week 2 onwards; IL-4 was only increased late in infection." (PMID 25398130, 2014). "Previous infection was associated with an accentuated immune response characterized by a significant production of IFN-γ, IL-5 and IL-10." (PMID 24401094, 2014). "IL-5 is the primary cytokine involved in the generation and maturation of eosinophils in the bone marrow and for the egress of eosinophils to sites of infection e.g. the IAV infected lungs." (PMID 24068930, 2013). "The precise role of eosinophils and IL-5 in the host response to IV infection is currently being evaluated." (PMID 24068930, 2013). "In agreement with this, immunization by repeated infection and sub-curative treatment led to high levels of IL-5, IL-10, IL-12, IL-13, IFN-γ, and TNF compared to uninfected mice, where levels were very low or undetectable." (PMID 24180253, 2013). "To investigate differential inflammatory responses associated with Lmo-InlA-mur-lux and Lmo-EGD-lux infections, we measured serum levels of IFN-γ, IL-10, TNF-α, IL-6, CCL2, IL-5 and IL-1β at 3 and 5 days p.i. using Luminex bead arrays." (PMID 23617550, 2013).
infection (continued). "The relationship between pre-treatment SWA-IgE, eosinophil number and infection intensity and the 24-hr post-treatment IL-5 boost was investigated in a Malian cohort (aged 5–40 yrs), exposed to S. haematobium." (PMID 23556029, 2013). "C-kit+ ILC2 are the predominant IL-5 producing cell type during the late, “recovery” phase of infection, that is following virus clearance." (PMID 24068930, 2013). "In the current study, it was found that infection of BALB/c mice with P. berghei K173 caused marked increases in plasma levels of pro- and anti-inflammatory cytokines including IL-5, IL-10, IL-12, IL-13, IFN - γ, and TNF." (PMID 24180253, 2013). "Several factors likely account for our inability to detect IL-5 in the airways at later time points during the resolution phase of infection." (PMID 24068930, 2013). "A strong CD4+ proliferative T-cell response was observed at the early stage of infection, and IFN-γ, IL-2, and IL-5 were produced within the first weeks after infection whereas the detection of IL-10 was slightly delayed." (PMID 22400039, 2012). "In this infection, eosinophils and/or IL-5 are essential components of the innate protective immune response." (PMID 22360486, 2012). "The protection was established within a few days after challenge infection and was characterized by L3-specific immunoglobulins, eosinophilia and high levels of IL-5." (PMID 22413031, 2012). "In contrast, the 13 bp deletion in smeZ did not appear to have marked effects on cytokine production elicited by GAS-M3 during in vivo invasive infection, with the exception of IL-5." (PMID 23049698, 2012). "IL-4R-/-/IL-5-/- DKO supported the infection better than any other strain (70 days), followed by IL-5-/- KO (50 days), IFN-γ-/-/IL-5-/- DKO (40 days), IFN-γ-/- KO (20 days) and lastly IL-4R-/- KO (5 days)." (PMID 22348321, 2012). "In a mouse model, treatment with anti-IL-4 and anti-IL-5 antibodies resulted in an increased level of infection compared to isotype antibody control animals." (PMID 22685452, 2012). "Infections in humans have been associated with eosinophils and TH2-type responses and re-stimulation of peripheral blood mononuclear cells showed strong IL-5 responses at the mRNA and protein level." (PMID 22360486, 2012). "For example, segregation analysis of a Brazilian population has revealed that susceptibility to infection is controlled by the SM1 (S. mansoni 1) gene locus that has been linked to the 5q31–q33 chromosome region comprising the genes for IL-4, IL-5, and IL-13." (PMID 22545160, 2012). "Worms recovered 70 days post infection in IL-4R/IL-5 DKO mice were young adults and measured 10.12 mm in length and 0.1 mm in width." (PMID 22348321, 2012). "In contrast, in primary infections in mice over-expressing IL-5, targeting of the larval stages by eosinophils occurs from day 10 post-infection, and the young adults become embedded in eosinophil-rich granulomas." (PMID 22360486, 2012). "The strain that best accommodated L. loa was the IL-4R-/-/IL-5-/- KO with larvae surviving up to 70 days post infection." (PMID 22348321, 2012). "Infection during (d0 NTHi+OVA) or after (d10 NTHi+OVA) sensitization resulted in significant reductions in OVA-induced IL-5, IL-13 and IFN-γ release from MLN T cells, compared to uninfected, allergic (OVA) controls." (PMID 21998577, 2011). "For example, acute infection of C57BL/6 mice with a high dose (200 eggs) of Trichuris results in a polarized Th2 cell response, characterized by high levels of IL-4, IL-5 and IL-13, and resistance to infection." (PMID 21573179, 2011). "Infection also induced significant but low level increases in NTHi-induced IL-5, IL-13, IL-17 and IL-22, and higher levels of IFN-γ release from mediastinal lymph nodes (MLN) cultures after 5 days, which returned to baseline levels after 26 days." (PMID 21998577, 2011). "Consistent with this, intestinal gene expression levels of Il4, Il5 and Il13 at day 14 post-infection were heightened in CD103−/− mice." (PMID 21573179, 2011).